EGFR (epidermal growth factor receptor)
Diseases named in the same sentence as EGFR in open-access papers (continued):
Sharing a sentence is not in itself a finding about the gene and the disease.
cancer (continued). "Since this was first demonstrated by EGF to EGFR-mediated signaling pathways, we now understand that similar signaling processes play a vital role in other key processes, such as migration of tumor cells and cancer metastasis." (PMID 35847914, 2022). "Uncovering the mechanisms that govern EGFR-mediated autophagy may prove valuable to understanding autophagy misregulation in cancers and how adapted autophagy affects resistance to anti-EGFR monoclonal antibody treatments." (PMID 35563080, 2022). "Interestingly, the anti-EGFR and anti-PEG bispecific Ab, that is, PEG engagerEGFR, bound both PEGylated liposomes containing doxorubicin (Doxisome) and EGFRs and showed antiproliferation activity in in vitro assay using EGFR-positive cancer cells." (PMID 36546903, 2022). "The ITs which target EGFR may be alternatives to anti-EGFR antibodies and can deliver the toxin moiety with diverse mechanisms of action to kill cancer cells and overcome cancer resistance." (PMID 36555466, 2022). "These compounds possess potential as EGFR inhibitors in cancer treatment." (PMID 36296495, 2022). "Here, we investigated the role of EGFR clusters in cancer and their dependence on EGF binding." (PMID 35612280, 2022). "As PFKP Y64 phosphorylation regulates PI3K/AKT in EGFR-activated cancer cells, we investigated whether PFKP Y64 phosphorylation could modulate SP1 activity." (PMID 36435833, 2022). "However, the effectiveness of existing anti-EGFR drugs for cancer diagnosis and treatment is limited, which calls for developing innovative therapeutic techniques to reduce EGFR signal transduction and expression." (PMID 36793341, 2022). "The epidermal growth factor receptor (EGFR) is a well-characterized cluster-based receptor tyrosine kinase that initiates signaling cascades promoting cell growth, proliferation, and differentiation and is therefore implicated in a variety of human cancers." (PMID 36340505, 2022). "In general, L-theanine could induce cancer cell apoptosis through the mitochondrial pathway, inhibiting the EGFR, NF-κB, and other signaling pathways, downregulating MMP9, or upregulating Smad2 in cancer treatment." (PMID 35445053, 2022). "Additionally, the epidemiologic data varied between different countries or regions, and there is limited information on subgroup analyses of different cancer stages and epidermal growth factor receptor (EGFR) expression." (PMID 36233811, 2022). "Other important pathways targeted by anti-cancer monoclonal antibodies are the epidermal growth factor receptor (EGFR)-, CD20-, vascular endothelial growth factor (VEGF)-, and the programmed cell death protein-1 (PD-1)/programmed cell death protein-1 ligand (PD-L1)-mediated pathways." (PMID 35804808, 2022). "The EGFR pathway is one of the prominent signaling cascades studied in relevance to the progression of human cancers, and it has been reported to be elevated in many types of cancers including NSCLC." (PMID 35744950, 2022). "While RON can be translocated jointly with EGFR, one can speculate that other partner RTKs could be involved in similar mechanisms and may vary by cancer type." (PMID 35454943, 2022). "Nrp2 has been reported to regulate epidermal growth factor receptor (EGFR) levels in cancer cells." (PMID 35158941, 2022). "In this work, several chalcones containing the ligustrazine moiety were synthesized and tested for their in vitro anticancer activity and several cancer markers, including EGFR, BRAFV600E, c-Met, and tubulin polymerization, in order to uncover multitarget bioactive compounds." (PMID 35424971, 2022). "Overview of EGFR-mutant cell lines included in the 134 cancer cell line panel." (PMID 36185300, 2022). "Under circumstances of EGFR driver mutation, the TKD is homeostatically activated in a ligand-independent manner, leading to transmission of excessive pro-survival and pro-proliferation signals and resulting in cancer initiation and progression." (PMID 35903676, 2022).
cancer (continued). "Internalization of boron clusters via EGFR-targeted receptors, resulting in boron accumulation in cancer cells overexpressing this receptor, may be a promising approach to treat tumors using BNCT." (PMID 36499115, 2022). "Together, our data indicate that EGFR-targeted hDT806 inhibits cancer cell proliferation and suppresses the growth of xenograft tumors by interfering with multiple cellular processes, such as the disruption of EGFR signaling, inhibition of transcription, DNA damage, as well as apoptotic response." (PMID 35453686, 2022). "New anticancer drugs targeting EGFR signaling have been developed to treat different types of cancer, including the EGFR tyrosine kinase inhibitors (TKIs), which directly inhibit EGFR tyrosine kinase activity and are currently being used for treating locally advanced or metastatic NSCLC." (PMID 35235599, 2022). "Some patients initially respond to tyrosine kinase inhibitors (TKI) but ultimately develop resistance: cancers acquire TKI-desensitizing EGFR mutations or activate compensatory signals, including WNT/β-catenin, the mechanistic target of rapamycin mTOR, and AKT signaling to drive cancer recurrence." (PMID 35461372, 2022). "For example, internalization of EGFR through a clathrin-dynamin-dependent mechanism recycles the receptor to the plasma membrane and prolongs EGFR activity, which may have a role in cell proliferation and cancer cell growth." (PMID 36010634, 2022). "We present novel single-molecule total internal reflection fluorescence microscopy of (i) EGF and EGFR in living cancer cells, (ii) the action of anti-cancer drugs that separately target EGFR and human EGFR2 (HER2) on these cells and (iii) EGFR–HER2 interactions." (PMID 35612280, 2022). "Compared to the selected radiomic features, diameter had no discriminative power regarding cancers with EGFR or ALK mutations, nor for histopathological types (all p > 0.050)." (PMID 35482262, 2022). "Although multiple studies have shown that afatinib may have advantages against cancers of the wild-type (WT)-EGFR, this chemical uniqueness is underexplored for clinical utility." (PMID 36291827, 2022). "It is FDA approved to treat a variety of EGFR-mediated cancers." (PMID 36199696, 2022). "In addition, panitumumab, cetuximab, brigatinib, and icotinib are other approved drugs targeting EGFR for the treatment of various types of cancers." (PMID 35744950, 2022). "The recent discovery of small-molecule tyrosine kinase inhibitors (TKIs) has led to favorable cancer profile drugs that target cancer-specific EGFR inhibitors such as gefitinib and erlotinib lapatinib, afatinib, canertinib, and angiogenesis inhibitors such as sorafenib, sunitinib, and axitinib." (PMID 36550571, 2022). "Thus, EGFR and its downstream signalling molecules have appeared as promising targets for cancer therapy in human and dogs." (PMID 34882994, 2022). "DZD9008 is a small molecule compound designed for EGFR/HER2 ex20ins mutant cancer." (PMID 35418149, 2022). "Transactivation and crosstalk between the EGFR and Wnt/β-catenin pathways may contribute to the aggressiveness of cancers." (PMID 35744950, 2022). "Physical aspects of the cellular microenvironment have been implicated as possible contributors to resistance development, and there is a growing realization that EGFR possesses kinase-independent (e.g., signaling independent) prosurvival functions in cancer cells." (PMID 35507881, 2022). "Elevated levels of EGFR relative to normal tissues were found for ten cancer types." (PMID 35455447, 2022). "Moreover, cooperation of EGFR signaling with Hh/GLI was demonstrated to promote cancer cells transformation and proliferation." (PMID 35752861, 2022). "Consequently, PEPDG278D strongly inhibits the growth of cancer cells and tumors overexpressing EGFR and/or HER2." (PMID 35650607, 2022).
cancer (continued). "NRP1 has recently been implicated in resistance to cancer therapies including oncogene-targeted therapies and chemotherapy through activation of bypass survival pathways, including receptor-tyrosine kinase pathways such as HER2, EGFR and IGF1R." (PMID 35078508, 2022). "EGFR overexpression has been involved in cancers, including NSCLC." (PMID 35402265, 2022). "Therefore, the dispute for the clinical improvement and utilization in cancer therapy of anti-EGFR agents alone and/or in combination with other SMIs/phytochemicals treatments would be the suitable assortment of potentially responding NSCLC patients." (PMID 35402265, 2022). "Briefly, C12orf59 suppression mediated the shedding of extracellular E-cadherin and contributed to activation and internalization of epidermal growth factor receptor (EGFR), resulting in enhanced activation of various downstream signals and subsequent cancer cell survival and invasion." (PMID 35860553, 2022). "Moreover, the evidence suggests that over-stimulation of the EGFR pathway seen in EGFR-induced cancers can lead to the expression of PD-L1 in human cancer cells." (PMID 37305016, 2022). "Here, we demonstrate in vitro dye-free optical imaging and successful gene transfection with luminescent SPION@bPEI, which was further modified for receptor-mediated delivery of the cargo selectively to cancer cell lines overexpressing the epidermal growth factor receptor (EGFR)." (PMID 35116215, 2022). "Overall, these results indicate that anti-EGFR CAR-T-cell-based therapy may have a high clinical potential in different cancer types." (PMID 36551506, 2022). "The ability of NIR-PITs to eliminate EGFR- or HER2-expressing cancer cells have been used to treat multiple types of tumors, including brain 33, head and neck 34, 35, bladder 36-38, lung 39-42, ovarian 43-45, breast 46-50, esophageal 51, and gastrointestinal 52-56 cancers." (PMID 36276636, 2022). "Elucidation of the emerging role of claudins in cancer stem-like properties and EGFR-TKI resistance as well as how to regulate claudins expression may inform the development of effective therapies against EGFR-TKI resistance." (PMID 35301287, 2022). "EGFR, a receptor tyrosine kinase, is a major regulator of cancer development." (PMID 35359830, 2022). "The overexpression and/or mutations of epidermal growth factor receptor (EGFR) family proteins, i.e., EGFR (HER1), ERBB2, ERBB3 and ERBB4, are often found in multiple types of cancer cells and are considered to be a significant prognostic indicator in the clinical intervention of cancer." (PMID 35163685, 2022). "Gefitinib, bevacizumab and recombinant human endostatin are the first-line treatment drugs for non-small cell lung cancer (NSCLC) with somatic epidermal growth factor receptor (EGFR) mutations in China, and were included in the first and second batches of the price-negotiated anti-cancer drugs." (PMID 35937254, 2022). "Moreover, blockade drugs for EGFR and PD-1 can enhance the effective of NKG2D, encoded by KLRK1, lead to cancer cell recognition and killing by NK effector cells." (PMID 35132098, 2022). "It was a need to develop novel tools for EGFR-mutated NSCLC, and CRISPR/Cas9 gene editing technology maybe a promising method to correct cancer-driven mutations for cancer therapy." (PMID 35935840, 2022). "Even under normoxic conditions, secreted SPINK1 protein enhances the radiation tolerance of cancer cells in a manner dependent on epidermal growth factor receptor (EGFR) and nuclear factor erythroid 2 related factor 2 (NRF2) and accelerates the growth of tumors after radiotherapy." (PMID 35223512, 2022). "Therefore, the effects of other miR-200 family members on the responses of cancer cells to anti-cancer drugs targeting EGFR should be examined." (PMID 35682560, 2022). "Fluorescent anti-EGFR was able to bind to the membranes of cancer cells." (PMID 35701793, 2022).
cancer (continued). "Moreover, the literature demonstrated that immuno-targeted combination therapies with anti-PD-1 or anti-PD-L1 inhibitors substantially prolonged PFS in EGFR WT cancer patients." (PMID 36230688, 2022). "EGFR is considered an established target for cancer therapy." (PMID 36499115, 2022). "As such, the IBC stemness might be forced and a loop between EGFR signaling, cancer cell stemness, and inflammation would sustain the cancer survival and progression." (PMID 36428610, 2022). "Recently, EGFR-based nanoplatforms have been widely explored against cancers." (PMID 36096856, 2022). "Moreover, targeting ERBB3 and EGFR signaling is an effective method for overcoming cancer progression and resistance to anticancer therapy." (PMID 35681658, 2022). "NSCLC patients with EGFR mutations exhibit high triggering receptor expressed on myeloid cells 2 (TREM2)-positive (+) TAM infiltrations with unique NSCLC molecular features and advanced cancer progression." (PMID 36439487, 2022). "Nonetheless, EGFR inhibitors, including the EGFR-blocking antibody cetuximab or EGFR kinase inhibitors, have had disappointing outcomes in the clinic, suggesting alternative mechanisms through which EGFR promotes or sustains the progression of these cancers." (PMID 35569509, 2022). "Our data indicated that 3′-UTR variations in HDAC9 and EGFR may promote cancer development through posttranscriptional regulation." (PMID 35654793, 2022). "Epidermal growth factor receptors (EGFRs; also known as ErbB1) are transmembrane glycoproteins with an intracellular tyrosine kinase and are members of the ErbB receptor family, with involvement in over 70% of all cancers." (PMID 36568260, 2022). "Given that the activation of EGFR signalling tends overall to inhibit autophagy, gefitinib and erlotinib inhibition of EGFR signalling was unsurprisingly found to induce autophagy in a dose-dependent manner and in multiple cancer cells of multiple origins)." (PMID 35158954, 2022). "This work demonstrates these limitations and proposes iodo silanes as a superior alternative to amino silanes via a case study involving the synthesis of MIP nanoparticles against epitopes of epidermal growth factor receptor (EGFR), a cancer biomarker of great clinical significance." (PMID 35458345, 2022). "The sensitivity of the phenocopy signatures in mutation-negative cancer cell lines was on par with DNA alterations for EGFR, BRAF, and MAPK, and better than DNA alterations for PI3K-AKT, PARP/HRD, ERBB2, MTOR, and JAK." (PMID 36253482, 2022). "Our results indicate that combination of EGFR-TKIs with HSP27 inhibitors may represent a good strategy to overcome resistance to EGFR-TKIs, especially in cancers exhibiting AKT pathway activation." (PMID 35931945, 2022). "Considering the importance of amplifications of EGFR in cancer, this mechanism of ST6Gal1 action may also contribute to oncogenesis and/or tumor progression." (PMID 36106023, 2022). "The clinical relevance of EGFR-positive cancers is underscored by their global incidence." (PMID 35213974, 2022). "Paradoxically, although EGFR could be beneficial in T1D, its role in the cancers we studied is mostly oncogenic." (PMID 36558071, 2022). "As suggested for other cancer types, a thiosemicarbazone-mediated decrease in EGFR observed in SH-SY5Y cells in the present study may be attributed to NDRG1 upregulation." (PMID 36160437, 2022). "Additionally, miRNAs are able to exert pro- or anti-cancer effects in different signaling pathways, including classical wnt/β-catenin, epidermal growth factor receptor (EGFR), and transforming growth factor (TGF-β), but the exact details are not yet clear." (PMID 36479040, 2022). "Recently, targeting EGFR degradation is considered a new cancer treatment strategy." (PMID 35614042, 2022).
cancer (continued). "Our results demonstrated that nuclear translocation of β-catenin is significantly reduced upon EPBS treatment, suggesting that it may be implemented alongside EGFR tyrosine kinase inhibitors in drug-resistant cancers." (PMID 35744950, 2022). "Taken together, these data demonstrate the critical role of EGFR kinase activity in normal tissue homeostasis and the response to injury, and the limitations of the use of TKIs and EGFR-targeting antibodies in patients with cancer due to their detrimental effect on normal tissue physiology." (PMID 36185288, 2022). "In our analysis, the EGFR L858R neoantigen was identified in an HLA subtype-specific manner that could be used to generate cancer vaccines in HLA A*33:03 subsets patients." (PMID 36505399, 2022). "In addition, the cost of using WES to determine TMB is about 10 times that of using cancer hot spot panel sequencing to determine EGFR and ATM status." (PMID 35521981, 2022). "We present the first single-molecule light microscopy observations of the effect on live human cancer cells of anti-cancer immunotherapy drugs cetuximab and trastuzumab which specifically and separately inhibit EGFR activation by targeting either EGFR or HER2, respectively." (PMID 35612280, 2022). "Activation of NF-κB and EGFR in a constitutive manner could be observed in multiple solid tumors and combined to provide oncogenic signals to cancer cells." (PMID 35049931, 2022). "In addition, EGFR was reported that it can blocked anti-cancer miRNA maturation under hypoxic status." (PMID 35924146, 2022). "Autophagy plays a dual role during malignant transformation, while EGFR is able to play a key regulatory role in determining whether autophagy inhibits or promotes cancer." (PMID 35831301, 2022). "Having established that ATM inhibition can be used to effectively target cancer cells that survive EGFR inhibitor therapy, we sought to evaluate whether these findings could be extended to other DDR pathway inhibitors through a similar mechanism." (PMID 35353542, 2022). "EGF family ligands are important activators of EGFR signaling in diverse cancers." (PMID 36506869, 2022). "TAMs may directly induce cancer cell proliferation by releasing growth factors such as epidermal growth factor receptor (EGFR), which promote the proliferation of cancer cells." (PMID 35183252, 2022). "Scientists have also developed liposomes combined with an anti-EGFR aptamer (Apt) to target EGFR muted cancer cells using erlotinib and later observed improvements in the reversal of hypoxia-induced resistance when they applied perfluorooctylbromide (PFOB) using the liposomal formulation." (PMID 35814435, 2022). "Epidermal growth factor receptor (EGFR) is a member of the human epidermal growth factor receptor (HER) family of receptor tyrosine kinases, and its abnormal expression is associated with the etiology of various cancers." (PMID 36387129, 2022). "In addition, the internalization and degradation of EGFR monoclonal antibody and receptor complexes can downregulate EGFR on the surface of cancer cells." (PMID 35840984, 2022). "Our findings suggest that CBD and CBG could be developed for EGFR TKIs-based treatment options in patients with EGFR-positive cancers." (PMID 36568260, 2022). "Activating mutations of proto-oncogenes such as EGFR, PI3K, and AKT as well as inactivating mutations of tumor suppressor PTEN or TSC1/2 causes the activation of the mTOR signaling pathway in a wide range of cancers." (PMID 35805935, 2022).